CCL5 (C-C motif chemokine ligand 5)
Diseases named in the same sentence as CCL5 in open-access papers (continued):
Sharing a sentence is not in itself a finding about the gene and the disease.
endometrial cancer (9 papers, 2019 to 2025). Primary or metastatic malignant neoplasm involving the endometrium (mucous membrane that lines the endometrial cavity). "In the analyzed cohort of women, we additionally found that the A-A haplotypes for the rs2107538-rs2280789 polymorphisms localized in the CCL5 gene were associated with an approximately twofold increase in the risk of endometrial cancer." (PMID 38001676, 2023). "The AA homozygotes in CCL5 rs2107538 were associated with more than a quadruple risk of endometrial cancer (p ≤ 0.050)." (PMID 38001676, 2023). "A multiple-SNP analysis determined A-A haplotypes, for both CCL5 polymorphisms and T-A-A haplotypes in the range of CCL2 and CCL5 SNPs to be associated with an approximately twice higher risk of endometrial cancer (OR 1.84 95% CI 1.21–2.81, and OR 1.71 95% CI 1.10–2.65, respectively, p ≤ 0.050)." (PMID 38001676, 2023). "A single-SNP statistical analysis showed more than a four times higher risk of endometrial cancer in the women with the AA homozygotic status within CCL5 −403 G>A polymorphism (OR 4.71 95% CI 1.80–12.34 in the codominant model and OR 4.63 95% CI 1.80–11.93 in the recessive model, p ≤ 0.050)." (PMID 38001676, 2023). "Based on the genetic results, obtained in our project and on the previously reported data on CCL5 levels in endometrial cancer, the A allele in rs2107538 may also contribute to altered CCL5 expression levels in the disease in question." (PMID 38001676, 2023). "This study is the first to explore the prognostic significance and immune activation roles of BATF, CD3G, KIAA1755 and CCL5 in endometrial cancer." (PMID 40356925, 2025). "Our study demonstrated that both the AA homozygotes in CCL5 rs2107538 and the GA heterozygotes in CXCR2 rs1126580 had significantly been associated with an increased risk of endometrial cancer." (PMID 38001676, 2023). "In this case-control study, we aimed to identify the possible associations between selected single nucleotide polymorphisms (SNPs), localized in the CCL2, CCL5, CXCL8, and CXCR2 genes, and the onset and progression of endometrial cancer." (PMID 38001676, 2023). "The A-A haplotypes for the CCL5 polymorphisms and T-A-A haplotypes for the CCL2 and CCL5 SNPs were associated with about a twofold risk of endometrial cancer (p ≤ 0.050)." (PMID 38001676, 2023). "In conclusion, CCL2 rs4586, CCL5 rs2107538 and rs2280789, and CXCR2 rs1126580 demonstrated significant associations with an increased risk of endometrial cancer." (PMID 38001676, 2023). "The reported case-control study of genetic associations was designed to establish the role of selected single nucleotide polymorphisms (SNPs) of the CCL2, CCL5, CXCL8, and CXCR2 genes in the onset and progression of endometrial cancer." (PMID 38001676, 2023). "CCL2 rs4586, CCL5 rs2107538 and rs2280789, as well as CXCR2 rs1126580, seem to be significantly associated with an increased risk of endometrial cancer in the population of Polish women." (PMID 38001676, 2023). "Although the effects of HMWH and LMWH on cytokine/chemokine or growth factor expression appear to differ among different conditions and cell lines, thus providing (at least in part) contradictory results, it has been observed that HMWH enhances the expression of CCL5 in endometrial carcinoma cells." (PMID 30935029, 2019). "The H-W equilibrium was observed for IL8 −738 T>A and CCL5 351 A>G SNPs among all the studied women, as well as for CXCR2 1440 G>A and CCL5 −403 G>A polymorphisms, among the patients with endometrial cancer and non-cancerous individuals, respectively (p ≤ 0.050)." (PMID 38001676, 2023). "Significant relationships with endometrial cancer were demonstrated, both for CCL2, CCL5, and CXCL8 chemokines and for the chemokine receptor CXCR2." (PMID 38001676, 2023). "The main cytokines secreted by CAFs isolated from human endometrial cancer tissue include MCP-1, CCL5, RANTES, interleukin-6, and -8 (IL-6, IL-8) VEGF, EGF, HGF, FGF-2, as well as TGFβ1 isoform." (PMID 34501347, 2021).
endometrial cancer (continued). "Therefore, five endometrial cancer cell lines were treated with DMSO, 100nM, 200nM, and 500nM of AZD1775, and qRT-PCR was employed to measure the expression of CCL5, CXCL10, and IFNB1." (PMID 38169513, 2024). "Considering endometrial cancer, a significant relationship was noted between its incidence and pathogenesis on the one hand and CCL2, CCL5, and CXCL8 chemokines, and their selected receptors, including CCR2 (the receptor for CCL2) and CXCR2 (the receptor for CXCL8) on the other." (PMID 38001676, 2023).
Hepatitis (9 papers, 2016 to 2026). Inflammation of the liver. "Although CCL3 and CCL5 are hepatitis associated, precisely how their expression is regulated remains unclear." (PMID 27994596, 2016). "Thus, both results suggest that CCL5 is hepatitis associated." (PMID 27994596, 2016). "In Ad-HBV-infected mice, CCL3 and CCL5 contributed to the recruitment of effector immune cells to the liver and promoted hepatitis." (PMID 27994596, 2016). "Considering the symptoms of hepatitis in patients with HBV-associated ALF and in patients of immune clearance phase, these data suggest that CCL5 is important in hepatitis B. Next, we tested the serum of HBV patients receiving continuous antiviral treatment." (PMID 27994596, 2016). "Immature neutrophils circulating in advanced MASH patients also expressed an array of pro-inflammatory chemokines that can aggravate and perpetuate liver inflammation, such as CCL2, CCL3, CCL5, CXCL1, and XCL2." (PMID 38791066, 2024). "As expected, when the hepatitis-related symptoms of ALT level and HBV DNA copy number decreased, the CCL5 concentration in the patient serum also decreased." (PMID 27994596, 2016). "The association between SOD1 (Cu2+/Zn2+-dependent superoxide dismutase) and CCL5 in the nervous system has not been reported; to date, such a relationship has only been identified in the context of hepatitis." (PMID 41508046, 2026). "Additionally, both pro-inflammatory and anti-inflammatory genes, such as Cd163, Ho-1, Il-1β, Il-10, and Ccl5, along with CD163 and HO-1 protein expression, were markedly suppressed, supporting the notion of alleviated liver inflammation." (PMID 41522337, 2026).
infarction (9 papers, 2014 to 2025). A localised pathological necrosis of tissue resulting from obstruction of the blood supply usually by a thrombus, an embolus, or vascular torsion. "Inhibition of CCL5 in translational models ofmyocardial infarction with or withoutcoronary reperfusion results in asmaller infarct size with a corresponding significant reduction in neutrophilinfiltration." (PMID 40747357, 2025). "Ccl5 has also been reported to be involved in postmyocardial infarction remodelling." (PMID 35194060, 2022). "Finally, based on our data, KC (CXCL1) and RANTES (CCL5) might also be considered important regulators of the immune response following prolonged myocardial I/R, as KC is significantly elevated in the serum and infarcted heart, peaking on day 1 after infarction." (PMID 30858476, 2019).
oral cancer (9 papers, 2012 to 2023). "Our results are concordant, suggesting CCL5 association with oral cancer progression upon WPS intake." (PMID 32961854, 2020). "Elevated CCL5 levels are significantly associated with oral cancer progression, relapse, and/or metastasis, as well as drug resistance, indicating its fundamental role in oral carcinogenesis." (PMID 32961854, 2020). "Similar to CCL5, CCL4 has analogous role in cancer progression; CCL4 enhances susceptibility to oral cancer." (PMID 32961854, 2020). "CCR 5 has two ligands, CCL3 and CCL5, and recently was reported that the axis composed by CCR5 and associated chemokines has pro-tumorigenic effect, playing an important role in oral cancer progression." (PMID 31011147, 2019). "We next explored the importance of CCL5 in the spread of tongue cancer, since CCL5 has been shown to promote the motility of oral cancer cells." (PMID 24204919, 2013). "CCL5 enhances oral cancer cell migration through the increase in MMP-9 production." (PMID 32961854, 2020). "Over-expression of CCR5 in oral cancer patients might protect tissue cells from CCL5-induced carcinogenesis by decrease the levels of free CCL5, and CCR5 rs1799987 G/A SNP might associate with oral cancer risk." (PMID 28404909, 2017). "Since CCL5 was previously shown to be a representative protein related to cancer invasion, we considered that CCL5 may be a key factor in oral cancer invasion upon rhBMP-2 treatment." (PMID 25271422, 2014). "Interestingly, CCL5 neutralizing antibodies significantly reduced the invasion of oral cancer cells." (PMID 25271422, 2014). "CCL5 (previously known as RANTES—Regulated on Activation, Normal T cell Expressed and Secreted) has been shown to play a crucial role in migration and metastasis in human cancer cell lines and further showed that that CCL5/CCR5 axis enhanced migration of oral cancer cells, probably via MMP-9." (PMID 24376459, 2013). "Both CCL5/CCR5 axis and CCL3/CCR5 axis may be involved in the migration and proliferation of oral cancer cells." (PMID 34124265, 2021).
prostate tumor (9 papers, 2009 to 2022). "CCL2 and CCL5 are closely related to prostate tumor metastasis and tumor resistance." (PMID 34367971, 2021). "Moreover, metastatic prostate tumors also exhibited increased CCL5 expression when compared with primary prostate tumors (p = 0.013)." (PMID 32300100, 2020). "In addition, results in the xenotransplant tumor model showed that CCL5 knockdown significantly inhibited the effect of MSCs on increasing the volume of prostate tumor in AD." (PMID 30257726, 2018). "Observations of the clinical behaviour of prostate tumors suggest that the increased secretion of IL-6 and CCL5 and the higher expression of PSMA may be correlated." (PMID 19242540, 2009). "To confirm our findings in human prostate tumors, we further examined the ERα, CD206, CCL5 and IL6 expressions in 14 human PCa tissue specimens by IHC staining." (PMID 26790618, 2016). "Human and murine prostate tumors have been previously reported to express CCL2, CCL5 and CXCL12." (PMID 27177227, 2016).
squamous cell carcinoma (9 papers, 2014 to 2026). A carcinoma arising from squamous epithelial cells. "In particular, the authors reported massive CCL5 and TGF-β production in a squamous cell carcinoma (SCC) tumor model, that is reverted by FAK kinase inhibition." (PMID 31500143, 2019). "Additionally, nuclear localization of FAK increases certain cytokines like CCL5 and CXCL10 levels, suggesting a potential immune response and possible immunotherapeutic treatments in uveal melanoma patients as demonstrated in squamous cell carcinoma." (PMID 40000790, 2025).
acute respiratory distress syndrome (8 papers, 2020 to 2025). Progressive and life-threatening pulmonary distress in the absence of an underlying pulmonary condition, usually following major trauma or surgery. "For example, it has been seen that higher levels of CCL5 are associated with worse outcomes, amplifying the inflammation process, and promoting the development of acute respiratory distress syndrome (ARDS)." (PMID 39590591, 2024). "The resulting acute respiratory distress syndrome (ARDS) and extrapulmonary multi-organ dysfunction are provoked by the excessive production of pro-inflammatory cytokines (IL-6, CXCL8) and chemokines (CXCL10, CCL5, CCL2), a phenomenon also referred as cytokine storm." (PMID 35013790, 2022). "TLR signaling pathways promote the production of IFN-α, IFN-β, IL-6, TNF, IFN-γ, CCL5, and IFN-stimulated genes, which are produced during acute respiratory distress syndrome (ARDS) and viral infections." (PMID 33953641, 2021).
airway hyperresponsiveness (8 papers, 2007 to 2025). "Yet, this chemokine can drive a Th2 response towards a Th1 response and the presence of CCL5 is linked to a decreased airway hyperresponsiveness during repeated allergen exposure." (PMID 41404114, 2025). "In mice, CCL5 was upregulated in parallel with a decline in airway hyperresponsiveness after repeated allergen challenge." (PMID 35743888, 2022). "It is reported that a number of chemokines such as CCL2, CCL5, CXCL10 are associated with RSV-induced airway hyperresponsiveness and CCL11, CCL17, and CCL 22 are involved in the development of pulmonary eosinophilia with RSV infection." (PMID 21980478, 2011). "Forty‐eight hours after the last OVA challenge, mice were assessed for airway hyperresponsiveness (AHR), cell composition and cytokine levels, including chemokine ligand 5 (CCL5), in bronchoalveolar lavage (BAL) fluid." (PMID 26612496, 2016).
brain injury (8 papers, 2017 to 2026). Acute and chronic (see also brain INJURIES, CHRONIC) injuries to the brain, including the cerebral hemispheres, CEREBELLUM, and brain STEM. "Our findings demonstrate that CCL5 plays a critical role in orchestrating microglial responses following mild traumatic brain injury." (PMID 41508046, 2026). "The present study identifies a unique role of the chemokine CCL5 in axonal regrowth after brain trauma." (PMID 39285280, 2024). "In an analogous manner, we now show that brain injury converges on TAM Ccl5 production through a different mechanism involving neuronal glutamate-induced oligodendrocyte IL-1β secretion, a key immunomodulator of brain injury." (PMID 38308315, 2024). "In brain trauma, the plasma level of CCL5 increases in both human patients and animals after injury." (PMID 39285280, 2024). "The expression of chemokines (e.g., CCL2, CCL5, CXCL10, and CXCL13) was also elevated in peripheral blood after brain injury and strongly associated with poor prognosis of TBI patients." (PMID 37208955, 2023). "Comparisons were made between sham-operated CCL5-KO mice, CCL5-KO mice receiving PBS, and those treated with CCL5 following mild traumatic brain injury (mTBI)." (PMID 41508046, 2026). "A close-head weight-drop system was used to induce mild brain trauma in C57BL/6 (wild-type, WT) and CCL5 knockout (CCL5-KO) mice." (PMID 39285280, 2024). "Both CCL5 and the GPX-1 precursor -NAC reduced neuronal OS, protected hippocampal neurons from death and promoted recovery of memory-cognition function in mice after mild brain injury." (PMID 41508046, 2026).
fibrosis (8 papers, 2010 to 2022). the formation of excess fibrous connective tissue in an organ or tissue in a reparative or reactive process. "Both CCL5 blockade and macrophage depletion contribute to alleviating pancreatic fibrosis and inflammation in MLN4924-treated CP mice." (PMID 33723230, 2021). "In addition, CCL5 and its related CCR5 ligand CCL3 and CCL4 are upregulated in the liver of patients with fibrosis." (PMID 33623529, 2021). "In line, hepatic mRNA expression of the chemokines ccl2 (F0-1 compared to F4 fibrosis, p = 0.0088) and ccl5 (F0-1 compared to F4 fibrosis, p<0.0001), but not of ccl3, was strongly up-regulated in fibrosis." (PMID 20548789, 2010). "The CCR2-CCR5 antagonist, cenicriviroc, which blocks chemotactic signaling of CCL2 (MCP-1), CCL3 and 4 (MIP-1α and β), and CCL5 (RANTES), showed encouraging phase 2b study results of improving fibrosis without worsening NASH activity and a phase 3 study is currently under way." (PMID 30643981, 2019).
glomerulonephritis (8 papers, 2004 to 2025). A renal disorder characterized by damage in the glomeruli. "Since CCL5/CCR5 participates in the formation of inflammatory infiltrates during glomerulonephritis, inhibition of CCR5 exerts renal protection during early glomerulonephritis through its anti-inflammatory properties." (PMID 32194402, 2020). "The humoral response and the Th1/Th2 balance in HAF-glomerulonephritis and mesangial cell proliferation in vitro were not affected by the CCL5/RANTES analogs." (PMID 15265234, 2004).
HCMV infection (8 papers, 2012 to 2025). "Rock2, Ccl5, Plk1, Rel, and Ctnnb1 are mainly associated with inflammatory responses, including positive regulation of IκB kinase/NF-κB signalling and human cytomegalovirus infection." (PMID 41007634, 2025). "Human cytomegalovirus (HCMV) infection in human VSMCs activates a novel IκB kinase (IKK)-related pathway involving TBK1, IRF3, and chemokines CCL5/RANTES and CXCL10/IP-10." (PMID 40980176, 2025).
Hodgkins lymphoma (8 papers, 2020 to 2025). A heterogeneous group of malignant lymphoid neoplasms of B-cell origin characterized histologically by the presence of Hodgkin and Reed-Sternberg (HRS) cells in the vast majority of cases. "High levels of CCL5 in Hodgkin's lymphoma tissue are correlated with monocyte infiltration and poor prognosis." (PMID 35702353, 2022). "Also, CCL5 secretion is increased when CD40 is cocultured with classical Hodgkin lymphoma cells or with MSCs derived from lymph nodes of Hodgkin lymphoma patients." (PMID 35702353, 2022). "Similarly, CCL5 secreted by classic Hodgkin lymphoma cells recruits MSCs and monocytes and enhances MSC proliferation and CCL5 secretion; conditioned medium from these MSCs increases tumor cell growth and monocyte migration." (PMID 33299638, 2020). "Similarly, CCL5 secreted by classic Hodgkin lymphoma cells recruited MSCs and monocytes, enhancing MSC proliferation and CCL5 secretion." (PMID 33330442, 2020).
invasive breast carcinoma (8 papers, 2018 to 2023). A carcinoma that infiltrates the breast parenchyma. "In particular, increased expression of CCL5 has been found to be associated with a more aggressive and invasive breast cancer phenotype." (PMID 36765778, 2023). "Local CCL5 expression was further shown to be elevated in invasive breast carcinoma in peritumoral tissue and was positively correlated with lymph node and distant metastases, underlining the tumor-promoting character of this chemokine." (PMID 37444610, 2023). "Similarly, circulating CCL5 was seen to increase with the number of involved lymph nodes in serum samples from invasive breast cancer patients." (PMID 32252260, 2020). "In our present study, we performed immunohistochemistry for CCL5 and its receptors, CCR1, 3 and 5, in 111 invasive breast carcinoma tissues." (PMID 33671956, 2021). "This represents an unreported role of CCL5 in specific ECM construction, which stands to illuminate ways of surgically excising, diagnosing, and treating invasive breast cancer." (PMID 32252260, 2020).